CHI3L1 (chitinase 3 like 1)
Diseases named in the same sentence as CHI3L1 in open-access papers (continued):
Sharing a sentence is not in itself a finding about the gene and the disease.
astrocytoma (12 papers, 2010 to 2024). "Besides, recently numerous studies emphasized chitinase-3-like protein 1 (CHI3L1), also known as YKL-40 as one of the most promising astrocytoma diagnostic and prognostic biomarker." (PMID 34162919, 2021). "One of the first demonstrated correlations between CHI3L1 expression and astrocytoma grade was established in 2002 by Tanwar and co-workers and later by other groups." (PMID 33227903, 2020). "Our results reinforce these studies: the measured average CHI3L1 concentration in the control group was lower compared to that for high-grade astrocytoma (40.4 ng/mL in low- and 51.1 ng/mL in high-grade astrocytoma (III and IV grade))." (PMID 33227903, 2020). "Further investigation will be required to evaluate CHI3L1 value as a molecular marker for astrocytoma prognoses and for novel treatment strategies against all grade astrocytomas." (PMID 27121858, 2016). "Multivariate analysis confirmed that astrocytoma grade, CHI3L1 mRNA expression level and patient age were considered as independent prognostic factors." (PMID 27121858, 2016). "Further investigation will be required to evaluate CHI3L1 as a molecular marker for astrocytoma prognoses and for novel treatment strategies against all grade astrocytomas." (PMID 27121858, 2016). "Furthermore, approximately one-quarter (27.7%) of all high-grade IDH1-wildtype astrocytoma patients had higher CHI3L1 protein concentrations in serum than the highest CHI3L1 value in the control group (66.1 ng/mL)." (PMID 33227903, 2020). "Our group demonstrated that integrating the values of CHI3L1 and OPN protein expression in serum with IDH1 mutational status into one parameter could predict patient 24-month survival with 86.8% accuracy for astrocytoma patients of all grades." (PMID 33227903, 2020). "We demonstrated that integrating serum CHI3L1 and OPN protein level values and tumor isocitrate dehydrogenase 1 IDH1 mutational status into one parameter could predict low-grade astrocytoma patients’ two-year survival with 93.8% accuracy." (PMID 33227903, 2020). "Kaplan–Meier analysis showed that lower CHI3L1 serum concentration is related to longer astrocytoma patient overall survival (Log-rank test; χ2 = 5.417; df = 1; p = 0.0199), while higher AREG concentration is related to worse survival prognosis (Log-rank test; χ2 = 3.968; df = 1; p = 0.0464)." (PMID 33227903, 2020). "We created an astrocytoma patient survival prediction model consisting of CHI3L1 and OPN expression levels and patient IDH1 mutational status, which predicted two-year astrocytoma patient survival with accuracy rates of 86.8% in all astrocytomas and 93.8% in low-grade astrocytomas (LGG)." (PMID 33227903, 2020). "In our study, we used real-time quantitative PCR (qRT-PCR) to measure the quantitative expression of CHI3L1 in different grade astrocytoma tissues without the influence of other malignancies or medical diseases." (PMID 27121858, 2016).
diabetic nephropathy (12 papers, 2015 to 2025). "MaR1 and CHI3L1 represent two critical molecules that exhibit opposing effects in the inflammation and fibrosis underlying diabetic nephropathy." (PMID 40731875, 2025). "Diabetic nephropathy (DN) is one of the most serious complications of DM, and Chi3l1 levels are closely associated with kidney function decline and mortality in both T1DM and T2DM patients." (PMID 39769202, 2024). "The serum CHI3L1 levels of patients with diabetic nephropathy were statistically lower than the control group." (PMID 40731875, 2025). "However, in our study, CHI3L1 levels were lower in patients with diabetic nephropathy compared to the control group." (PMID 40731875, 2025). "However, CHI3L1 levels were significantly lower in the diabetic nephropathy group compared to the control group." (PMID 40731875, 2025). "Recent findings indicate elevated plasma levels of CHI3L1 in diabetic patients, which may correlate with the progression of diabetic nephropathy." (PMID 40731875, 2025). "Therefore, we hypothesized that in diabetic nephropathy, levels of the pro-inflammatory/fibrotic marker CHI3L1 would be elevated, while levels of the pro-resolving mediator MaR1 would be altered as part of a compensatory response." (PMID 40731875, 2025). "In this study, we investigated the relationship between serum MaR1 and CHI3L1 levels and inflammation parameters in patients with T2DM and diabetic nephropathy." (PMID 40731875, 2025). "The aim of this study was to investigate the serum levels of MaR1 and CHI3L1 and their relationship with inflammatory parameters such as NLR and PLR in patients with T2DM and diabetic nephropathy." (PMID 40731875, 2025).
fibrosis (12 papers, 2010 to 2025). the formation of excess fibrous connective tissue in an organ or tissue in a reparative or reactive process. "In CHB-related fibrosis, serum CHI3L1 levels are elevated and positively associated with fibrosis stages." (PMID 40821115, 2025). "All the results imply that serum CHI3L1 offered the best diagnostic performance in the diagnosis of advanced fibrosis." (PMID 35360517, 2022). "Furthermore, Chi3L1 promoted the differentiation of SSc dermal fibroblasts into myofibroblasts, and Chi3L1‐deficient (Chi3L1‐/‐) mice showed amelioration of fibrosis in a bleomycin‐induced SSc (BLM‐SSc) model." (PMID 39686726, 2025). "However, their findings showed that the diagnostic value of serum CHI3L1 for significant and advanced fibrosis was limited by low sensitivity and specificity." (PMID 35360517, 2022). "This elucidates why serum levels of CHI3L1 are significantly elevated in patients with autoimmune liver disease-related fibrosis compared to healthy controls, and why higher levels are associated with increased severity of fibrosis." (PMID 40352927, 2025). "A study indicated that the accuracy of joint diagnosis of fibrosis by using serum CHI3L1 levels and HA levels was higher than that of using serum CHI3L1 levels alone." (PMID 38003338, 2023). "For CHC-related fibrosis, CHI3L1 levels correlate with the severity of HCV-related fibrosis." (PMID 40821115, 2025). "Furthermore, diagnostic models using fibrosis markers other than CHI3L1 outperform CHI3L1 in diagnosing HCV-related fibrosis." (PMID 40821115, 2025). "Furthermore, Chitinase-3-like protein 1 (CHI3L1) was found to promote cardiac fibrosis through upregulation of TUG1 in mice treated with Ang II." (PMID 38259314, 2023). "CHI3L1 can be used to predict, diagnose, and evaluate the severity and response to treatment of NAFLD or related fibrosis." (PMID 40821115, 2025). "However, many studies found that CHI3L1 alone may not be as effective as single biomarkers like CK-1889,90 or sSiglec-791 in diagnosing NAFLD-related fibrosis." (PMID 40821115, 2025).
non-small cell lung carcinoma (12 papers, 2010 to 2025). A group of at least three distinct histological types of lung cancer, including non-small cell squamous cell carcinoma, adenocarcinoma, and large cell carcinoma. "Given CHI3L1’s role in remodeling after injury, increased CHI3L1 serum levels are also associated with metastasis in non-small cell lung cancer." (PMID 37374908, 2023). "CHI3L1, an indicator of the inflammatory and immune status of the body, has been shown to be associated with the prognosis of patients with malignant tumors such as colon, breast, ovarian, and non-small cell lung cancers." (PMID 40260255, 2025). "Idgf2 is a member of the conserved chitinase-like protein (CLP) family including CHI3L1/YKL-40 and CHI3L2/YKL-39 which are implicated in inflammatory diseases and a variety of cancers including colon and non-small cell lung cancer." (PMID 33370287, 2020). "A report has shown that elevated pretreatment serum concentration of CHI3L1 serves as an independent prognostic biomarker for poor survival in patients with metastatic non-small cell lung cancer." (PMID 23613996, 2013). "High CHI3L1 expression and serum levels have been found in both non-small-cell lung carcinoma (NSCLC) and small-cell lung carcinoma (SCLC) patients, and they have been linked to worse overall survival, a poorer response to chemotherapy, and worse chemotherapy responses." (PMID 36615523, 2022). "Both non-small-cell lung carcinoma (NSCLC) and small-cell lung carcinoma (SCLC) patients have been reported to show high CHI3L1 expression and serum levels, and these have been reported to be associated with poorer overall survival." (PMID 36615523, 2022).
Obstructive Sleep Apnea (12 papers, 2014 to 2024). "However, in patients with type 1 diabetes reduced NO in the blood correlated with elevated CHI3L1, and plasma CHI3L1 was negatively associated with nitric-oxide mediated vasodilatory capacity in adults with obstructive sleep apnea." (PMID 29448936, 2018). "Additionally, Chi3l1 levels can be used to diagnose and assess the severity of obstructive sleep apnea syndrome (OSAS), with the concentrations of Chi3l1 in serum showing better diagnostic capabilities for moderate and severe OSAS than those in plasma." (PMID 39769202, 2024). "The aim of this preliminary observational study was to assess the roles and interaction of obstructive sleep apnea (OSA) severity and body mass index (BMI) with plasma CHI3L1 levels and CHIT1 activity in patients with moderate to severe OSA." (PMID 30311184, 2018).
ischemic stroke (11 papers, 2012 to 2025). A stroke disorder caused by obstruction of blood flow to the brain, due to thrombotic (local blood clot formation) or embolic (due to a blood clot or other material traveling from another site) event. "A notable discovery in this field is the association of CHI3L1 levels in CSF and plasma with the prognosis of ischemic stroke." (PMID 39827337, 2025). "This paradox underscores the intricate role of CHI3L1 in ischemic stroke and highlights the need for maintaining its levels within an optimal range to mitigate neuroinflammation and improve outcomes." (PMID 39827337, 2025).
liver cancer (11 papers, 2018 to 2025). An epithelial or non-epithelial malignant neoplasm that arises from the liver. "Overall, the association between CHI3L1 and these target proteins in liver cancer suggests that CHI3L1 plays an important role in liver cancer progression and metastasis and that targeting CHI3L1 is a potential therapeutic approach for liver cancer." (PMID 38177294, 2024). "The high text-mining score of CHI3L1 suggests a significant association with liver cancer, similar to those of the representative marker proteins EGFR and VEGF." (PMID 38177294, 2024). "Moreover, the CHI3L1 rs880633 C allele was also correlated with the risk of liver cancer and higher serum CHI3L1 levels compared with the rs880633 T allele." (PMID 37902124, 2023). "Furthermore, higher plasma pro-inflammatory markers sTNF-R1 and CHI3L1, lipid metabolic abnormalities, sarcopenia, and risk of tumor recurrence were found to be concurrently associated based on multi-omics studies examining the main pathways connecting sarcopenia and liver cancer." (PMID 39014376, 2024). "Elevated serum CHI3L1 levels correlate with disease severity in a variety of human tumors, including breast, colon, prostate, ovarian, brain, thyroid, lung, and liver cancers, leading to poorer prognosis and shorter survival." (PMID 39445005, 2024). "In fact, CHI3L1 can modulate TGF-β signaling in liver cancer through the regulation of SMAD Family Member-2 (SMAD-2) and SMAD-364." (PMID 38177294, 2024). "CHI3L1 promotes an inflammatory response in liver cancer cells by activating signaling pathways that induce the production of proinflammatory cytokines, such as IL-6 and TNF-α." (PMID 38177294, 2024). "CHI3L1 can also regulate liver cancer potentially by regulating the TGF-β signaling pathways with activating kinase to phosphorylate SMAD2 and SMAD3." (PMID 34991559, 2022). "We also find the expression of CHI3L1 at both the protein and RNA levels is higher in liver cancer tissues than those in the normal liver tissues using both proteomic and transcriptomic analysis." (PMID 30301907, 2018). "To assess the in vivo metastatic potential of CHI3L1 overexpression or knockdown in liver cancer cells, we injected the HepG2-shCHI3L1, Bel7404-CHI3L1 and their control cells into the tail veins of nude mice." (PMID 30301907, 2018). "This study demonstrated for the first time the roles of CHI3L1 in liver cancer carcinogenesis and suggested that CHI3L1 was a potential target for developing liver cancer therapy." (PMID 30301907, 2018). "To study the role of CHI3L1 in migration and invasion of liver cancer cells, we performed transwell migration, invasion and wound healing assays." (PMID 30301907, 2018). "In our study, we found that the overexpression of CHI3L1 can promote cell proliferation, migration and invasion using in vitro in HepG2 and Bel7404 liver cancer cell model and in vivo using mice models." (PMID 30301907, 2018). "To gain a more comprehensive understanding of the mechanism of the CHI3L1’s global impact on liver cancer cells, we did RNA-seq analysis to gain a more comprehensive genome-wide understanding of the gene expression changes." (PMID 30301907, 2018). "CHI3L1 has also been shown to be involved in the development and progression of liver cancer." (PMID 38177294, 2024). "Furthermore, CHI3L1 regulates signaling pathways in liver cancer that are involved in tumor growth and progression." (PMID 38177294, 2024). "We used the Open Targets Platform to validate the link between CHI3L1 and liver cancer." (PMID 38177294, 2024). "We showed that, both in vivo and in vitro, overexpression of CHI3L1 could promote liver cancer cells growth, migration and invasion." (PMID 30301907, 2018). "Targeting CHI3L1 may have therapeutic potential in liver cancer." (PMID 38177294, 2024). "Moreover, the 3.3X overexpression of CHI3L1 in NF could promote as reported for liver cancer cell migration and invasion." (PMID 31601895, 2019).
liver cancer (continued). "We hypothesize that CHI3L1 promotes cell proliferation and migration in liver cancer cells." (PMID 30301907, 2018). "Lower panel: Elevated CHI3L1 levels increase VEGFA expression through the ERK1/2 and Akt pathways, promoting angiogenesis in liver cancer." (PMID 38177294, 2024). "Moreover, another study found that CHI3L1 increased the TNF-α-induced proliferation, migration, and invasion of liver cancer cells." (PMID 38177294, 2024). "On the other hand, CHI3L1 may negatively regulate S100A9 and S100A4, which means that its interaction with S100A9 and S100A4 results in a reduction in the proinflammatory effects of S100A9 and S100A4 in liver cancer." (PMID 38177294, 2024).
allergic disease (10 papers, 2010 to 2023). An immune response that occurs following re-exposure to an innocuous antigen, and that requires the presence of existing antibodies against that antigen. "CHI3L1 is known to be important in various diseases such cancers, allergic diseases, and inflammatory diseases 19-21." (PMID 37215572, 2023). "It is important to understand the precise biological function of CHI3L1 in the pathogenesis of cancer, allergic diseases, and inflammatory diseases." (PMID 37215572, 2023). "Here, we show that, consistent with the prior allergy studies, Chi3l1 regulates the IL-4+IL-13+ TH2 response to Hp infection." (PMID 37575256, 2023). "Thus, both mouse and human data support a role for YKL-40/Chi3l1 in promoting atopy and allergic disease." (PMID 37575256, 2023). "CHI3L1 has been studied extensively in the setting of human allergic disease." (PMID 37575256, 2023). "Several studies investigated the association of genetic variation in CHI3L1 with allergic diseases, but the SNP rs10399931 has not been reported in that context." (PMID 27193312, 2016). "The aberrant expression of chitinase 3-like-1 (CHI3L1) is involved in the pathogenesis of inflammatory and allergic diseases." (PMID 20390107, 2010). "Among these, chitotriosidase, acidic mammalian chitinase (true chitinases), and BRP-39/YKL-40 (CHI3L1; a chitinase-like protein or CLP) may have chitin-like targets and can modulate host immune responses during infections, allergy, tissue injury, inflammation, and tumor." (PMID 35482710, 2022).
Brain atrophy (10 papers, 2020 to 2025). Partial or complete wasting (loss) of brain tissue that was once present. "Interestingly, CSF CHI3L1 levels were associated with the development of brain atrophy evaluated by the brain parenchymal fraction change as well as cervical cord atrophy, both leading to increase disability in MS patients." (PMID 36988727, 2023). "The CHI3L1 (chitinase-3-like protein 1) level in the CSF was strongly correlated with brain atrophy, and the CSF levels of CXCL1, MMP-9, CCL22, CXCL13, and CXCL10 were correlated with the development of new lesions in T2 MRI." (PMID 34602928, 2021). "Also, there was a highly statistically significant good positive correlation between presence of MRI brain atrophy and CSF level of CHI3L1 (p > 0.001, r = 0.581)." (PMID 36988727, 2023).